PHLDA1 (pleckstrin homology like domain family A member 1)
Diseases named in the same sentence as PHLDA1 in open-access papers (continued):
Sharing a sentence is not in itself a finding about the gene and the disease.
asthma (3 papers, 2018 to 2023). "PHLDA1 (pleckstrin homology-like domain, family A, member 1) has only been associated with asthma diseases by our group." (PMID 31143187, 2019). "Previously reported overexpressed (IL-10, MSR1, PHLDA1, SERPINB2, and CD86) and underexpressed genes (CHI3L1, CPA3, IL-8, and PI3) in severe asthma were analyzed by RT-qPCR in peripheral blood mononuclear cells (PBMCs)." (PMID 37445432, 2023). "In a recent work, new gene and protein biomarkers CHI3L1, IL-8, IL-10, MSR1, PHLDA1, PI3, and SERPINB2, were proposed to discriminate healthy control subjects from nonallergic asthmatic patients (T2-low) and to measure asthma severity." (PMID 31143187, 2019).
cholangiocarcinoma (3 papers, 2024 to 2025). A carcinoma that arises from the intrahepatic biliary tree (intrahepatic cholangiocarcinoma) or from the junction, or adjacent to the junction, of the right and left hepatic ducts (hilar cholangiocarcinoma). "In general, brain, ovarian, cholangiocarcinoma, and uterine cancers were associated with high PHLDA1 expression and poor prognoses." (PMID 38921000, 2024). "In cholangiocarcinoma, a negative correlation was found between the PHLDA1 expression and such clinicopathological features as tumor site and histological grade." (PMID 39630301, 2025). "Moreover, a correlation was shown between PHLDA1 overexpression and a negative prognosis in breast, ovary, lung, brain, and cholangiocarcinoma cancers 3), as analyzed using PrognoScan and the Kaplan–Meier Plotter databases." (PMID 38921000, 2024).
gastric adenocarcinoma (3 papers, 2018 to 2025). "Also, in gastric adenocarcinoma, the expression of PHLDA1 protein was correlated with less malignant phenotype, e.g., decreased invasion and metastasis, decreased tumor size, and lower histological grade." (PMID 39630301, 2025). "Additionally, decreased expression of PHLDA1 in gastric adenocarcinoma correlates with decreased overall survival and increased tumor size, grade and metastasis." (PMID 39630301, 2025).
glioblastoma (3 papers, 2024 to 2025). The most malignant astrocytic tumor (WHO grade IV). "We observed that 754, 5076, 12768, and 4043 genes positively correlated with PHLDA1 expression in glioblastoma (GBM), colon (COAD), ovarian (OV), and pancreatic (PAAD) cancers, respectively." (PMID 38921000, 2024). "Another finding showed that PHLDA1 protein levels exhibited a prognostic value in glioblastoma." (PMID 39630301, 2025).
lung carcinoma (3 papers, 2008 to 2024). "As for immunity, PHLDA1 was first identified as the exhaustion gene of Tregs in colon and lung cancer." (PMID 38780041, 2024).
oral cancer (3 papers, 2018 to 2022). "In oral cancer, PHLDA1 was overexpressed, which acted as an apoptosis suppressor and was associated with advanced clinical stage of oral cancer." (PMID 30410722, 2018). "Hydrogen sulfide exposure enhanced the expression of PHLDA1 in an oral cancer cell line, Ca9-22, but not in normal oral keratinocytes, and knockdown of PHLDA1 in Ca9-22 cells induced apoptosis." (PMID 34405011, 2021).
colitis (2 papers, 2022 to 2025). Inflammation of the colon. "In this study, we report that T-cell death-associated gene 51 (TDAG51/PHLDA1) is a novel regulator of the development of dextran sulfate sodium (DSS)-induced colitis in mice." (PMID 36450854, 2022). "PHLDA1 was also found to be a positive regulator of intestinal inflammation and pyroptosis, and the knockdown of PHLDA1 in mice model of colitis, was characterized by the decreased proinflammatory response." (PMID 39630301, 2025). "Additionally, the knockdown of PHLDA1 evoked similar events in mice after dextran sulfate sodium-induced colitis." (PMID 39630301, 2025).
cystic teratoma (2 papers, 2022 to 2024). "From our previous report, DUSP5 and PHLDA1 mutations in mature cystic teratomas of the ovary identified on whole‐exome sequencing may explain teratoma characteristics in terms of osteogenic differentiation and hair growth." (PMID 38907278, 2024).
endotoxemia (2 papers, 2022 to 2025). "In endotoxemia, PHLDA1 inhibits pro-inflammatory responses by repressing the TLR4/MyD88/NF-κB pathway through TOLLIP." (PMID 39735680, 2025). "Although PHLDA1 has gotten increasing attention over the past 20 years, its role in endotoxemia remains to be elucidated." (PMID 35237256, 2022). "Our study provides a new vision for exploring the function of PHLDA1 and a new therapeutic target for endotoxemia." (PMID 35237256, 2022). "PHLDA1 may be a novel therapeutic target in treating endotoxemia." (PMID 35237256, 2022).
intestinal tumors (2 papers, 2014 to 2015). "Recent publications showed that TDAG51 (PHLDA1) is also highly expressed in other tumor types such as colon and intestinal tumors, which represents epithelial stem cell features." (PMID 26320182, 2015).
metastatic melanoma (2 papers, 2008 to 2018). A melanoma that has spread from its primary site to another anatomic site. "PHLDA1 has been reported to be involved in apoptosis signaling in T-cell and metastatic melanoma cells." (PMID 29736818, 2018).
oral squamous cell carcinoma (2 papers, 2025). "Moreover, expression of PHLDA1 as analyzed by immunohistochemistry in tissue microarray was associated with an advanced clinical stage and histological grade of oral squamous cell carcinomas and was postulated to be an independent prognostic factor by multivariate analysis." (PMID 39630301, 2025). "Additionally, in oral squamous cell carcinoma, tissue microarray analysis followed by immunohistochemistry revealed that the expression of PHLDA1 corresponded to a higher clinical stage and, therefore, a worse prognosis for patients." (PMID 39630301, 2025).
pancreatic adenocarcinoma (2 papers, 2025). "The high expression of PHLDA1 was associated with decreased overall survival, relapse-free survival, and a poor prognosis in patients with pancreatic adenocarcinoma." (PMID 39630301, 2025). "Another study showed the high expression of PHLDA1/3 as assessed by immunohistochemical staining in pancreatic adenocarcinoma tissues and using the Human Protein Atlas database." (PMID 39630301, 2025).
renal fibrosis (2 papers, 2025 to 2026). A final common manifestation of a wide variety of chronic kidney diseases characterized by glomerulosclerosis and tubulointerstitial fibrosis. "PHLDA1 promotes IL-1β expression and the knockout of PHLDA1 suppressed NF-κB signaling and renal fibrosis." (PMID 41727481, 2026).
subarachnoid hemorrhage (2 papers, 2023 to 2025). A serious neurological disorder characterized by intracranial hemorrhage into the subarachnoid space. "The study showed that PHLDA1 deficiency reduced proinflammatory cytokines production, NLRP3 inflammasome signaling, and neuronal apoptosis after subarachnoid hemorrhage." (PMID 39630301, 2025). "The role of PHLDA1 in neuroinflammation was found in C57BL/6 mice model after subarachnoid hemorrhage, bleeding in the space between the brain and the membrane that covers it." (PMID 39630301, 2025).
teratoma (2 papers, 2022 to 2024). A non-seminomatous germ cell tumor characterized by the presence of various tissues which correspond to the different germinal layers (endoderm, mesoderm, and ectoderm). "For example, the mutation p.Gln204del of the PHLDA1 gene was observed in all teratomas in this study." (PMID 36289533, 2022). "Moreover, novel mutations in DUSP5 and PHLDA1 genes found on whole-exome sequencing may help to explain the characteristics of teratomas." (PMID 36289533, 2022). "Moreover, novel mutations in DUSP5 and PHLDA1 genes found on WES may help to explain the characteristics of teratoma." (PMID 36289533, 2022).
brain cancer (1 paper, 2024). A primary or metastatic malignant neoplasm affecting the brain. "PHLDA1 was also discovered to be expressed in relation to a variety of cancers, including lung, bladder, liver, and brain cancers." (PMID 38921000, 2024). "During this multiomics analysis, we found that among the PHLDA family, PHLDA1 may be a therapeutic target for several cancers, including kidney, colon, and brain cancer, while PHLDA2 can be a therapeutic target for cancers of the colon, esophagus, and pancreas." (PMID 38921000, 2024).
brain injury (1 paper, 2025). Acute and chronic (see also brain INJURIES, CHRONIC) injuries to the brain, including the cerebral hemispheres, CEREBELLUM, and brain STEM. "The involvement of PHLDA1 in mitophagy mediated by FUN14 Domain-Containing Protein 1 (FUNDC1) in ischemic brain injury has recently been reported." (PMID 39630301, 2025).
breast tumor (1 paper, 2014). "PHLDA1 is downregulated in primary breast tumors by immunohistochemistry." (PMID 25238247, 2014).
cystic teratomas of the ovary (1 paper, 2022). "Among the prevalent mutated genes, 7 with the same variant in exons with changes in protein coding are important for the development of mature cystic teratomas of the ovary: PTGFRN, DUSP5, MPP2, PHLDA1, PRR21, GOLGA6L2, and KRTAP4-2." (PMID 36289533, 2022).
Ewing sarcoma (1 paper, 2022). A small round cell tumor that lacks morphologic, immunohistochemical, and electron microscopic evidence of neuroectodermal differentiation. "In summary, we presume PHLDA1 is a key regulator in the tumorigenesis and progression of Ewing sarcoma." (PMID 36092920, 2022). "PHLDA1 (key DEeRNA) was extensively expressed in cancer stem cells of Ewing sarcoma, which might play a critical role in the tumorigenesis of Ewing sarcoma." (PMID 36092920, 2022). "All these results showed that PHLDA1 and RASD1 (key DEeRNAs) were extensively expressed in cancer stem cells of Ewing sarcoma, which were potential targets for tumor treatment." (PMID 36092920, 2022).
ischemia (1 paper, 2018). A hypoperfusion of the BLOOD through an organ or tissue caused by a PATHOLOGIC CONSTRICTION or obstruction of its BLOOD VESSELS, or an absence of BLOOD CIRCULATION. "We also found a similar extent of PHLDA1 overexpression in cardiac muscle cells under ischemia conditions." (PMID 29736818, 2018). "Collectively, these results indicated that PHLDA1 changed faster than LDH activity in ischemia cardiac muscle cell." (PMID 29736818, 2018). "Moreover, the overexpression of PHLDA1 was also observed in cultured cardiac cells under ischemia." (PMID 29736818, 2018).
ischemic stroke (1 paper, 2023). A stroke disorder caused by obstruction of blood flow to the brain, due to thrombotic (local blood clot formation) or embolic (due to a blood clot or other material traveling from another site) event. "A more direct study indicated that PHLDA1 blockade inhibited neuroinflammation after ischemic stroke by balancing microglial M1/M2 polarization." (PMID 36875102, 2023).
liver disease (1 paper, 2024). "Herein, this study establishes the relevance of TDAG51/PHLDA1 protein levels in human liver disease." (PMID 38237682, 2024).
male infertility (1 paper, 2019). The inability of the male to effect fertilization of an ovum after a specified period of unprotected intercourse. "Hence, the role of hypothetical PHLDA1-mediated mechanisms involved indirectly in the death of spermatogenic cells deserves further studies, also in the context of stress-related male infertility." (PMID 31906015, 2019).
pancreatitis (1 paper, 2022). Inflammation of the pancreas. "Our results showed that high PHLDA 2/3 expression was significantly associated with a history of pancreatitis (p = 1.838 × 10−2/p = 8.663 × 10−3), and the high expression of PHLDA1/2 was significantly correlated with a worse initial treatment effect (p = 0.003/p = 0.045)." (PMID 36142223, 2022).
Peritoneal Fibrosis (1 paper, 2021). Disorder characterized by a wide range of structural changes in PERITONEUM, resulting from fibrogenic or inflammatory processes. "While it is known that PHLDA1/TDAG51 is induced by the UPR and is necessary for the development of TGF-β adenovirus-mediated peritoneal fibrosis, the mechanism by which TDAG51 affects the progression of fibrosis, and specifically renal interstitial fibrosis in CKD, has not yet been studied." (PMID 34625532, 2021).
retinoblastoma (1 paper, 2024). A malignant tumor that originates in the nuclear layer of the retina. "By performing lentiviral infection on retinoblastoma cell line Y79, we found that the MOI of lentiviral vectors was positively correlated with the protein expression level of PHLDA1." (PMID 39012348, 2024).
sarcoma (1 paper, 2024). A usually aggressive malignant neoplasm of the soft tissue or bone. "Furthermore, gastric, liver, and sarcoma tumors were associated with reduced PHLDA1 expression." (PMID 38921000, 2024).
viral infection (1 paper, 2024). "The results showed consistent up-regulation of PHLDA1 across different cell types upon different viral infections, suggesting PHLDA1 is a key intracellular regulator upon viral infections." (PMID 39012348, 2024). "Further analysis of single-cell transcriptome data revealed that the expression of the photoreceptor cell differentiation regulatory gene PHLDA1 was up-regulated after virus infection." (PMID 39012348, 2024). "Our findings suggest that PHLDA1 may have a role in promoting the interferon pathway in other immune systems, however, the specific functions of this pathway in other viral infection systems still require further research." (PMID 39012348, 2024). "By analyzing transcriptome data from various cell types infected with different viruses, we found that PHLDA1 was commonly upregulated, suggesting that PHLDA1 up-regulation may be a common response of various cell types to viral infection." (PMID 39012348, 2024). "As a downstream target gene of PHLDA1, it has been that PRDM1 is an important transcriptional repressor that plays multiple roles in viral infection." (PMID 39012348, 2024).
tumor (44 papers, 2008 to 2025). "The accelerated growth observed in PHLDA1-silenced tumors aligned with previous studies that implicated PHLDA1 as a tumor suppressor in various cancers." (PMID 41430389, 2025). "PHLDA1 has been identified as a gene that is associated with a variety of tumors and as one that promotes tumor growth." (PMID 39012348, 2024). "Compared with the control, the weights and volumes of tumours in the PHLDA1 downregulation group were decreased, while the PHLDA1 plasmid caused an increase in tumour weight and volume." (PMID 31189920, 2019). "Moreover, we showed that silencing of PHLDA1 in vivo caused changes in tumor growth, morphology, vascularization and ECM structure." (PMID 41430389, 2025). "Moreover, although pan-cancer analysis highlights the broad prognostic and immunomodulatory relevance of PHLDA1, interpretation of these cross-tumor associations must be tempered by the fact that expression patterns and downstream signaling networks can vary dramatically between tumor lineages." (PMID 40688078, 2025). "Moreover, retinoid signaling has been reported to downregulate key EMT‐associated transcription factors—many of which overlap with PHLDA1 downstream effectors—thereby providing a mechanistic rationale for TTNPB’s potential efficacy in disrupting CAF–tumor crosstalk." (PMID 40688078, 2025). "The role of PHLDA1 in cancer is the best characterized as dichotomous, demonstrating either oncosuppressor or oncogenic features depending on the type of tumor." (PMID 39630301, 2025). "The study showed that the miR-526b-5p-PHLDA1 mRNA binding is regulated by circ_0085539, a circular RNA to be upregulated in this tumor." (PMID 39630301, 2025). "Although our study focused on the enrichment of PHLDA1 in mCAFs and its association with ECM remodeling and tumor invasion, it is important to place these findings within the broader context of CAF heterogeneity." (PMID 40688078, 2025). "New experimental studies are required to establish the PHLDA1 role as a tumor suppressor gene or oncogene and its impact on tumor progression." (PMID 39630301, 2025). "The dichotomous role of PHLDA1 in cancer is evidenced more widely, being both pro- and antiapoptotic depending on the tumor type, cell milieu, and the insult." (PMID 39630301, 2025). "The major aim of the publication is to review proapoptotic or antiapoptotic roles of PHLDA1 in cancer, including ample evidence on PHLDA1 role as a tumor suppressor gene or oncogene and its influence on tumor progression." (PMID 39630301, 2025). "Pan-cancer analysis further supported PHLDA1’s prognostic and immunomodulatory significance across multiple tumor types." (PMID 40688078, 2025). "Our in vivo experiments revealed that xenograft tumors derived from PHLDA1-silenced cells were larger and more densely packed than control tumor cells, hemorrhagic, and their collagen network was more abundant than that of tumors grown from control cells." (PMID 41430389, 2025). "Downregulating PHLDA1 in CAFs dramatically decreased tumor cell proliferation activity, and similar results were achieved in colony formation assays." (PMID 40688078, 2025). "In particular, we postulate that a specific subset characterized by elevated PHLDA1 expression plays a pivotal role in mediating the crosstalk between malignant ductal cells and the tumor microenvironment." (PMID 40688078, 2025). "Here, we introduce a novel 7-gene risk model that not only robustly stratifies PC patients but also unveils the unique role of PHLDA1 as a key mediator in tumor-stroma crosstalk." (PMID 40688078, 2025). "Then, separately via Bonferroni correction with a p-value < 0.05 for each case, we created a query to find the list of genes that correlated with PHLDA1 in different tumor types." (PMID 38921000, 2024). "Within glioblastoma, ovarian cancer, and colon cancer, PHLDA1 has been identified as an oncogene, involving in tumor cell proliferation, anti-apoptosis, and migration." (PMID 39033192, 2024).